EGFR (epidermal growth factor receptor)
Diseases named in the same sentence as EGFR in open-access papers (continued):
Sharing a sentence is not in itself a finding about the gene and the disease.
glioblastoma (continued). "In glioblastoma, EGFR aberrations frequently found also include mutations and various deletions in the extracellular domain of EGFR, with the truncated variant EGFRvIII, which lacks exons 2–7, being the most common deletion." (PMID 36185288, 2022). "Conversely, IDH wild-type tumors that do not fulfill morphological WHO grade 4 criteria are still diagnosed as glioblastoma if they exhibit at least one of the following alterations: EGFR amplification, a + 7/−10 genotype or TERT promoter mutation." (PMID 36333286, 2022). "On the other hand, some molecular alterations associated with neurological tumors have already been detected in plasma cfDNA, such as the number of MYCN copies in neuroblastoma or specific somatic mutations in glioblastoma (EGFR and IDH1)." (PMID 35563270, 2022). "The resistance of glioblastoma to various therapies is largely a result of an exceptionally mutated genome and increased activity of tyrosine kinase receptors, such as EGFR, which is typically upregulated in glioblastoma." (PMID 36294938, 2022). "Disregulated expression of EGFR occurs in approximately 40% of glioblastoma patients, and its mutation, EGFRvIII, reaches 20 to 30% of glioblastoma." (PMID 36040678, 2022). "Half of the EGFR-amplified glioblastomas carry a tumor-specific deletion variant (EGFRvIII), which is characterized by the in-frame deletion of exons 2–7, resulting in constitutive EGFR activation." (PMID 34681618, 2021). "We noted that these misclassified tumors rarely exhibit SCNA features commonly associated with IDH-wildtype glioblastoma such as + 7/ − 10 and EGFR amplification." (PMID 34863298, 2021). "Gene amplification and mutation of the oncogene epidermal growth factor receptor (EGFR) occur in ~60% of glioblastoma patients and is an indicator for poor prognosis in glioblastoma patients." (PMID 34771501, 2021). "The genetic criteria for a diagnosis of IDH-wildtype glioblastoma are stated as TERT promoter mutation or EGFR gene amplification or +7/−10 chromosome copy number changes." (PMID 34948010, 2021). "The splice variant III (EGFRvIII) is the most common EGFR mutation in glioblastoma and is found in 31% of patients." (PMID 34676470, 2021). "The epidermal growth factor receptor variant type III (EGFRvIII) is the most common mutation of EGFR in glioblastoma multiforme (GBM) and is found in approximately 25% of all GBMs." (PMID 33283409, 2021). "EGFR amplification, deletion, point mutations, and/or translocation are reported in more than half of glioblastomas." (PMID 34925034, 2021). "Prediction of EGFR has been performed in several radiomic studies using SVM classifiers with approximately 80–85% accuracy in defining EGFRvIII mutation in glioblastoma which exhibits more aggressive features and deep peritumoral infiltration." (PMID 34676470, 2021). "Over-expression of the EGFR in glioblastoma is often accompanied by rearrangements of the EGFR gene leading to the expression of EGFR variants." (PMID 33801941, 2021). "Epidermal growth factor receptor (EGFR) is associated with oncogenesis in glioblastoma, and substantial evidence supports a key role for EGFR in glioma progression." (PMID 34568049, 2021). "Our findings suggest that amplification of LANCL2 and EGFR were the independent diagnostic biomarkers for glioblastoma patients, and LANCL2 amplification was a significant prognostic factor for OS in younger glioblastoma patients." (PMID 34461927, 2021). "The mutations of EGFR are found in about 40% of glioblastomas but are seldom present in lower-grade gliomas." (PMID 34676470, 2021). "EGFR is the most frequently altered receptor tyrosine kinase (RTK) in glioblastoma, but amplification and activating mutation or fusions have been also reported in other RTKs, such as PDGFRA, MET, FGFR, and NTRK1." (PMID 34572759, 2021). "Glioblastoma cells have been reported to have high Cav-1 expression in association with EGFR-vIII (mut)." (PMID 34490102, 2021).
glioblastoma (continued). "EGFR variant III (EGFRvIII) is the most common variant of the EGFR observed in human tumors and is expressed in about 30% of newly diagnosed glioblastomas." (PMID 34066067, 2021). "In the EGFR gene, missense mutations, amplification, and rearrangement are commonly detected in glioblastoma tumors." (PMID 34769339, 2021). "Gefitinib acts by inhibiting EGFR and the amplification and mutation of EGFR in glioblastoma render it resistant to the clinical effects of the EGFR inhibitor gefitinib and the EGFR-targeting antibody cetuximab." (PMID 34065757, 2021). "For example, mutation in the tumor-specific mRNA of epidermal growth factor receptor was detected in EVs from serum of patients with glioblastoma." (PMID 33761899, 2021). "Approximately 40% of glioblastomas overexpress EGFR, with the most common variant being EGFRvIII, arising from the loss of exons 2-7 from the EGFR coding sequence." (PMID 34054867, 2021). "Here, we tested the specificity, safety and efficacy of R-613, the first oncolytic HSV fully retargeted to EGFRvIII, a variant of the epidermal growth factor receptor carrying a mutation typically found in glioblastoma." (PMID 34578259, 2021). "There are many specific genetic changes in glioblastoma cases, and the most frequently mutated or deregulated gene is epidermal growth factor receptor (EGFR), which is amplified in approximately 60% of glioblastomas." (PMID 33708242, 2021). "A clinical study demonstrated that using an anti-EGFRvIII-CAR in patients with glioblastoma, resulted in antigen loss and downregulation of the EGFR/EGFRvIII receptor appeared to promote T-cell resistance." (PMID 34831068, 2021). "One of the most common genetic aberrations associated with glioblastoma is epidermal growth factor receptor (EGFR) amplification." (PMID 34681618, 2021). "The relevant microRNAs, miR-524-3p and miR-524-5p, were suppressed in glioblastoma and the suppression was associated with EGFR overexpression and the EGFRvIII mutation." (PMID 34206026, 2021). "CAV1 encodes Caveolin1, a negative regulator of EGFR activation, which acts as a tumor suppressor gene in glioblastoma (GBM) cells." (PMID 33407894, 2021). "In other carcinomas like leukemia, glioblastoma, and colorectal, gastric, breast, and hepatocellular carcinomas EGFR mutation frequency reported to be low." (PMID 33736612, 2021). "EGFR (epidermal growth factor receptor), a member of the ErbB tyrosine kinase receptor family, is commonly found amplified and/or mutated in near 60% of glioblastoma (GBM), the most aggressive brain tumour." (PMID 34831480, 2021). "EGFR mutation and amplification were classified as prognostic biomarkers because they are abundant in glioblastoma cells." (PMID 34210107, 2021). "Primary glioblastomas typically display EGFR overexpression, CDKN2A (p16) deletions, PTEN (MMAC1) mutations, and MDM2 amplification." (PMID 33804731, 2021). "EGFR mutations, frequently combined with overexpression, are important drivers of human cancers, particularly in glioblastoma (found in 50%), NSCLC (15–20%) and colorectal cancers (3%)." (PMID 33995103, 2021). "Among the five overlapping interacting partners was RICTOR, which caught our attention due to its molecular connection to the majority of Lpd associated functions, EGFR-related signaling, and glioblastoma radioresistance." (PMID 34771501, 2021). "It was reported that CD151-α3β1 integrin complex can interact with EGFR to promote tumor invasion of glioblastoma, and integrin-associated CD151 can promote progression and metastasis of tumor mediated by ErbB2." (PMID 34108040, 2021). "Deletion of the proximal CTD (residues 958–1030, termed the ΔvIVb variant identified in glioblastoma multiforme patients), which removes the C1025 palmitoylation site, enhances EGFR signalling as measured by phosphorylation of the downstream MAPK effector Erk." (PMID 34610265, 2021).
glioblastoma (continued). "Another important facet in this context is the expression of mutated forms of the EGFR and that molecular-targeted therapies against mutated EGFR failed so far to improve glioblastoma patient overall survival." (PMID 34771501, 2021). "Glioblastoma oncogenesis has long been linked to epidermal growth factor receptor (EGFR) gene amplification, mutations and constitutive activation." (PMID 34577582, 2021). "EGFR is amplified in approximately 40% of glioblastoma patients and is often associated with high-grade tumors." (PMID 34210107, 2021). "Changes in EGFR expression due to copy number aberrations and mutations in the EGFR gene are among the features of glioblastoma." (PMID 32158381, 2020). "The BT112 cell line was derived from a glioblastoma with high-level EGFR amplification and expression of the mutant receptor variant EGFRvIII, which is maintained in vitro." (PMID 32178271, 2020). "They recommended TERT promotor (TERTp) mutation, EGFR highcopy amplification and/or combined chromosome 7 gain and 10 loss as a marker to identify tumors with glioblastoma-like outcome on a molecular scale." (PMID 32758285, 2020). "TAAs identified in glioblastoma multiforme include variant III of the epidermal growth factor receptor, HER2, CD133 and B7-H3." (PMID 32899932, 2020). "Glioblastoma-derived CTCs presented EGFR amplification, which is linked with the presence of EGFRvIII and aggressiveness of the disease." (PMID 31979318, 2020). "The PI3K–Akt signaling pathway is activated in most glioblastoma via either growth factor receptor activation, such as EGFR, or through loss of PTEN, a negative regulator of Akt activation." (PMID 33256086, 2020). "The gene encoding EGFR is among the most frequently amplified and mutated in several types of cancer including glioblastoma multiforme (GBM), which is the most lethal and one of the most common primary brain tumors." (PMID 33238647, 2020). "The EGFR amplification is associated with most of the glioblastoma (GBM) cases, with EGFRVIII being the most detected variant." (PMID 32391048, 2020). "EV EGFR is now being explored as an alternative diagnostic and prognostic marker to tissue EGFR in cancers including breast, lung, glioblastoma, ovarian and prostate." (PMID 33143170, 2020). "This study shows that the specific dPCR assay using LNA-hydrolysis probes from UPL® is a reliable and simple method to simultaneously detect an EGFR amplification and EGFRvIII variant, and this can be used in clinical practice in glioblastoma." (PMID 32303258, 2020). "In non-small cell lung cancer (NSCLC) or glioblastoma where EGFR driver mutation (EGFR-mut) and/or gene amplification are prevalent, mTOR activation contributes to disease progression, metastasis and tyrosine kinase inhibitor (TKI) resistance." (PMID 32923403, 2020). "This is especially true for common glioblastoma mutations such as the mutations of the epidermal growth factor receptor (EGFR)." (PMID 32117316, 2020). "The introduction of a constitutive activating EGFR mutant variant, EGFRvIII, in glioblastoma cells has been shown to exert a similar effect where tumor cells exhibit greater reliance on lipogenesis." (PMID 32872164, 2020). "The prevalence of EGFR mutation is far higher in glioblastoma than it is for NSCLC—suggesting its greater importance in glioblastoma biology." (PMID 33187135, 2020). "It was reported that ARF1 gene promoter methylation is associated with EGFR gene amplification and can promote the distinct tumor infiltration in glioblastoma." (PMID 32894165, 2020). "Intriguingly, it has been reported that the classic subtypes of glioblastoma are characterized by high frequencies of EGFR amplification and mutations." (PMID 32051553, 2020).
glioblastoma (continued). "EGFR alterations (amplifications, point mutations, and rearrangements) are found in about half of glioblastomas." (PMID 33396284, 2020). "Though EGFR was one of the first molecule linked to oncogenesis of glioblastoma, targeting it has been challenging in this disease." (PMID 32290213, 2020). "Something similar happens with EGFR, with relatively high mutation frequencies in glioblastoma (24%), lung adenocarcinoma (7%) and glioma (6%), but below 1% in the remaining 30 cancer types." (PMID 32239503, 2020). "Yet, in other studies in human glioblastoma cell lines, hypoxia caused increased expression of EGFR via HIF2α and upregulation of miR-134 expression." (PMID 32258065, 2020). "We evaluated whole-genome miRNA expression profiling associated with different EGFR amplification patterns in 30 cases of primary glioblastoma." (PMID 33396457, 2020). "EGFRvIII, deletion of exons 2 through to 7 (residues 6–273), is the most common EGFR mutation in glioblastoma." (PMID 33187135, 2020). "While TERTp mutation occurs with similar frequency in IDH-wildtype glioblastoma and lower-grade astrocytoma, EGFR amplification and 7+/10− appear to occur more frequently in IDH-wildtype GBM." (PMID 32640746, 2020). "For example, most EGFR mutations in brain tumors (glioblastoma and lower grade glioma) are located near its dimerization interface." (PMID 32239503, 2020). "It has been demonstrated that berberine-induced down-regulation of EGFR causes senescence in Glioblastoma cells." (PMID 33082482, 2020). "EGFR alterations, such as overexpression or mutations, have been frequently observed in several cancers, including glioblastoma (GBM), and are associated to uncontrolled cell proliferation." (PMID 32823532, 2020). "Taken together, using these results, the EGFR3 assay and the EGFR2/EGFR3 assay were selected to detect EGFR-amplified glioblastoma and to identify the EGFRvIII variant in the validation cohort." (PMID 32303258, 2020). "Patient 32 carried V659E TMD mutation and was also detected to carry the extracellular EGFR missense mutation A289V which has been previously reported as an oncogenic mutation in glioblastoma." (PMID 32478891, 2020). "Amplification of double minute chromosomes of the epidermal growth factor receptor gene (EGFR) is a frequent event in IDH-wildtype glioblastomas, while EGFR point mutations are comparatively rare." (PMID 30967140, 2019). "There has been an explosion of knowledge in the past decade in the understanding of the biological functions of EGFR and its associated pathways in glioblastoma." (PMID 31013819, 2019). "The patients having telomerase reverse transcriptase mutation, epidermal growth factor receptor amplification which are similar to glioblastoma, experience poor prognosis." (PMID 30276676, 2019). "It has been suggested that glioblastoma cell lines with helical domain mutations are still sensitive to dual PI3Ki/MEKi treatment, which is consistent with our observation that the EGFR-signaling pathway is adjustable in cell line SF767." (PMID 31438847, 2019). "Glioblastoma multiforme is characterized as an aggressive disease driven by EGFR amplification and mutations, limited in therapies due to the challenge of crossing the blood–brain–barrier." (PMID 31215437, 2019). "Epidermal growth factor receptor (EGFR) is mutated or amplified in 35–45% of IDH-wildtype glioblastomas and implicated as a key driver." (PMID 31073965, 2019).
glioblastoma (continued). "Approximately 50% of EGFR-amplified glioblastomas express epidermal growth factor receptor (EGFR) variant III (EGFRvIII) resulting from the in-frame deletion of exons 2–7." (PMID 31284441, 2019). "Here, we describe recent knowledge on the signaling pathways mediated by EGFR/EGFR variant III (EGFRvIII) with regard to current therapeutic strategies to target EGFR/EGFRvIII amplified glioblastoma." (PMID 31013819, 2019). "The CL molecular subtype of glioblastoma is strongly associated with an astrocytic signature, and amplified or hyperactive EGFR is a hallmark feature of glioblastoma cells with an astrocyte-like signature." (PMID 31632393, 2019). "About half of glioblastomas withEGFR amplification also contain deletions in exons 2–7.The product of EGFRvIII mutation is a constitutively active EGFR variantstimulating tumor angiogenesis in malignant gliomas." (PMID 31413876, 2019). "In line with this, glioblastoma-derived CTCs presented EGFR amplification that was linked to aggressiveness and was associated with the presence of EGFRvIII." (PMID 31284524, 2019). "EGFR gene (chromosome 7) overexpression and amplification occur because of genetic alteration, which is associated with glioblastoma and reported in the 2016 WHO classification." (PMID 31013819, 2019). "EGFR variant III (EGFRvIII) was found to potentiate IL-1β-induced IL-6 secretion through the p38 MAPK-MK2-HuR pathway in glioblastoma cells." (PMID 31772161, 2019). "EGFR status is also determined, amplification of which, in combination with the EGFRvIII mutation, is associated with glioblastoma." (PMID 31747973, 2019). "EGFR amplification, overexpression, or mutation is present in approximately half of glioblastomas and other malignant CNS tumors, including ependymoma and medulloblastoma, in both children and adults." (PMID 31903167, 2019). "We have successfully applied this model to identify the interconnections altered in the constitutive signaling of the mutated EGFR by comparing EGF-dependent and wild-type EGFR signaling in glioblastoma multiforme." (PMID 31386654, 2019). "We report the frequency of IDH mutations in a large cohort of nearly 1550 patients, EGFR amplifications in almost 1900 IDH-wildtype glioblastomas, and histone mutations in 70 adult gliomas." (PMID 30786920, 2019). "The EGFR gene also commonly incurs an intragenic deletion of exons 2–7 producing a constitutively active variant protein called EGFR-vIII, occurring in a quarter to half of glioblastoma." (PMID 30967140, 2019). "Targeting epigenetic regulators in glioblastoma can also modulate the activity of EGFR and its associated pathways." (PMID 31013819, 2019). "One potential molecular target amplified in 36% of glioblastoma patients is the epidermal growth factor receptor (EGFR), and the expression of EGFR is associated with prognosis in cancer." (PMID 31438847, 2019). "EGFRvIII is a glioblastoma-specific EGFR mutation consisting of a deletion that causes constitutive activity of tyrosine kinase contributing to glioblastoma aggressiveness." (PMID 30871102, 2019). "In human glioblastoma cells, the epidermal growth factor receptor (EGFR) is implicated as a downstream mediator of hypoxic effects." (PMID 31698752, 2019). "Blocking of STAT signaling using a combination of EGFR and Janus kinase inhibitors has been associated with apoptosis of cells in glioblastomas." (PMID 31013819, 2019). "The gene that encodes the EGF Receptor (EGFR) is over-expressed in up to 50% of all glioblastomas and in many of these tumors, EGFR is mutated to generate a constitutively active derivative called EGFRvIII50,51." (PMID 29445239, 2018). "Modulation of EGFR expression by gain-of-function and loss-of-function strategies in glioblastoma cancer stem cell lines enhances and reduces their tumorigenic ability, respectively, suggesting a key role of EGFR in gliomagenesis." (PMID 30279357, 2018).